DCUN1D4 (defective in cullin neddylation 1 domain containing 4)
Description:
Contributes to the neddylation of all cullins by transferring NEDD8 from N-terminally acetylated NEDD8-conjugating E2s enzyme to different cullin C-terminal domain-RBX complexes which are necessary for the activation of cullin-RING E3 ubiquitin ligases (CRLs).
Synonyms: DCNL4; KIAA0276
Tractability: PROTAC: UniProt records ubiquitination sites on it; ubiquitination databases record sites on it; a small molecule that binds it is known.
Gene: Protein-coding gene on chromosome 4 (51,843,000 to 51,916,839, forward strand). Ensembl gene ENSG00000109184.
Subcellular location: Nucleus
Subcellular location (Human Protein Atlas): Vesicles; Nucleoplasm
Pathways (Reactome):
Metabolism of proteins: Neddylation
Gene Ontology:
Molecular function: cullin family protein binding; protein binding; ubiquitin conjugating enzyme binding; ubiquitin-like protein binding
Biological process: positive regulation of protein neddylation; protein neddylation
Cellular component: nucleus; ubiquitin ligase complex
Genetic constraint (gnomAD): Loss-of-function variants: 15 observed, 29.34 expected, observed/expected ratio (o/e) 0.51, 90% interval 0.34 to 0.79. The upper end of that interval is the gene's LOEUF score, 0.79, which puts it in group 3 of 6, group 1 being the genes least tolerant of losing a copy. Missense variants: 242 observed, 283.18 expected, observed/expected ratio (o/e) 0.85, 90% interval 0.77 to 0.95. Synonymous variants: 107 observed, 97.74 expected, observed/expected ratio (o/e) 1.09, 90% interval 0.94 to 1.29.
Homologues: Orthologues: pig DCUN1D4 (99% identical), chimpanzee DCUN1D4 (97% identical), mouse Dcun1d4 (97% identical), rabbit DCUN1D4 (96% identical), dog DCUN1D4 (96% identical), guinea pig DCUN1D4 (94% identical), rat Dcun1d4 (94% identical), zebrafish dcun1d4 (83% identical), macaque DCUN1D4 (60% identical), Drosophila melanogaster SCCRO4 (49% identical), Drosophila melanogaster SCCRO (25% identical), Caenorhabditis elegans dcn-1 (24% identical). Paralogues in human: DCUN1D5 (56% identical), DCUN1D1 (28% identical), DCUN1D2 (27% identical), DCUN1D3 (26% identical).
Diseases named in the same sentence as DCUN1D4 in open-access papers:
DCUN1D4 is named in the same sentence as 1 disease in open-access papers, as found by Europe PMC text mining. Sharing a sentence is not in itself a finding about the gene and the disease.
DCUN1D4 shares sentences with these, for which no sentence is quoted: cancer (1 paper).